RNU6-334P (RNA, U6 small nuclear 334, pseudogene)
Gene: Small nuclear RNA gene on chromosome 5 (104,780,288 to 104,780,389, reverse strand). Ensembl gene ENSG00000252881.
Homologues: Orthologues: chimpanzee U6 (99% identical), macaque U6 (94% identical), guinea pig U6 (75% identical), pig U6 (74% identical). Paralogues in human: RNU6-35P (85% identical), RNU6-1031P (84% identical), RNU6-1227P (83% identical), RNU6-140P (83% identical), RNU6-338P (83% identical), RNU6-1056P (82% identical), RNU6-1124P (82% identical), RNU6-116P (82% identical), RNU6-1316P (82% identical), RNU6-16P (82% identical), RNU6-17P (82% identical), RNU6-18P (82% identical), and 1285 more.